CYP2C19 (cytochrome P450 family 2 subfamily C member 19)
Diseases named in the same sentence as CYP2C19 in open-access papers (continued):
Sharing a sentence is not in itself a finding about the gene and the disease.
Hypertension (19 papers, 2015 to 2026). The presence of chronic increased pressure in the systemic arterial system. "Study has shown that the interaction of CYP2C19*3 and smoking was independent risk factor for hypertension in a Uighur population from China." (PMID 37024851, 2023). "Combination of genotypes CYP2C8 rs7909236 TT and CYP2C19 rs4244285 GG was associated with increased hypertension risk in a Russian population." (PMID 37024851, 2023). "The purpose was to investigate the relationship of cytochrome P450 2C19 (CYP2C19) polymorphisms with hypertension in Hakka population." (PMID 37024851, 2023). "Third, this study did not investigate the relationship between the full-length variation of CYP2C19 gene, gene expression and the risk of hypertension." (PMID 37024851, 2023). "CYP2C19 loss-of-function (IM, PM genotypes) is independent risk factor for hypertension susceptibility." (PMID 37024851, 2023). "Studies have found that CYP2C19 gene polymorphisms increased the risk of hypertension in Russian and Chinese Han populations, and a study from Kumamoto University Hospital in Japan found that CYP2C19 variants are associated with microvascular angina." (PMID 37024851, 2023). "The proportion of IMs (49.3% vs. 42.9%), PMs (14.3% vs. 8.9%) (P < 0.001), and CYP2C19*2 allele (33.8% vs. 25.7%, P < 0.001) in hypertension group was significantly higher than that in control group." (PMID 37024851, 2023). "When considering CYP2C19 variants, clinicians can improve the efficiency of clinical prediction of hypertension risk." (PMID 37024851, 2023). "A study from the Han Chinese population showed that the CYP2C19 rs10509676 polymorphism is associated with hypertension." (PMID 37024851, 2023). "Our study found that CYP2C19 IM and PM genotypes were risk factors for hypertension in a cohort with a certain number of Hakka people." (PMID 37024851, 2023). "The proportion of CYP2C19 rs4244285 G/A genotype (46.0% vs. 39.6%, P < 0.001), A/A genotype (10.8% vs. 5.9%, P < 0.001), and A allele (33.8% vs. 25.7%, P < 0.001) in hypertension group was significantly higher than that in control group." (PMID 37024851, 2023). "The genotype and allele distributions of CYP2C19 rs4244285 were significantly different between hypertension group and control group." (PMID 37024851, 2023). "The proportion of intermediate metabolizers (IM) (49.3% vs. 42.9%), poor metabolizers (PM) (14.3% vs. 8.9%) (P < 0.001), and CYP2C19*2 allele (33.8% vs. 25.7%, P < 0.001) in hypertension group was significantly higher than that in control group." (PMID 37024851, 2023). "In summary, the association between CYP2C19 genotypes and hypertension was identified in a cohort study in Meizhou, China." (PMID 37024851, 2023). "In this study, we found that the CYP2C19-rs3814637 and -rs11568732 genotypes were significantly associated with the occurrence of hypertension and hemoptysis." (PMID 35814206, 2022). "Single-nucleotide polymorphisms in CYP2C19 are significantly associated with hypertension, hemoptysis, and anlotinib peak concentrations." (PMID 35814206, 2022). "CYP2C19 genotype is associated with the metabolism of compounds influencing both renal function and hypertension." (PMID 33931109, 2021). "CYP2C19 IM + PM phenotypes, advanced age, overweight, history of smoking, history of alcoholism, hypertension, and dyslipidemia may be associated with CAS in T2DM." (PMID 41658609, 2026). "However, in the specific population with hypertension, is there still an association between CYP2C19 gene polymorphism and susceptibility to CAD?" (PMID 40715000, 2025). "Some studies have proposed that the genotypes CYP2C19 *1/*2, *1/*3, *2/*2 and the CYP2C19 IM/PM phenotypes may contribute to a heightened risk of developing hypertension." (PMID 38671468, 2024). "At present, the relationship between hypertension and CYP2C19 polymorphism is still controversial." (PMID 37024851, 2023).
Hypertension (continued). "On the contrary, a study from a Korean population found that the CYP2C19*3 defective allele may contribute to reduced risk for the development of hypertension." (PMID 37024851, 2023). "We found that CYP2C19 *1/*2, *1/*3, *2/*2 genotypes, and the CYP2C19 IM, PM phenotypes may increase risk of hypertension." (PMID 37024851, 2023). "After adjusting gender, age, smoking, and alcohol consumption, we found CYP2C19 *1/*2, *1/*3, *2/*2 genotypes, and the CYP2C19 IM, PM genotypes may increase risk of hypertension." (PMID 37024851, 2023). "In this study, we investigated whether common polymorphisms of CYP2C19 gene are associated with hypertension susceptibility in Hakka population." (PMID 37024851, 2023). "The possible mechanism that CYP2C19 gene variant increases the risk of hypertension is that CYP2C19 gene variant reduces the activity of CYP2C19, and the lower activity of CYP2C19 significantly weakens the effect of vascular endothelial relaxation and vascular relaxation." (PMID 37024851, 2023). "Multivariate logistic regression (adjusted for gender, age, smoking, and drinking) indicated that CYP2C19 *1/*2, *1/*3, and *2/*2 genotypes may increase susceptibility to hypertension." (PMID 37024851, 2023). "CYP2C19 rs12721054 may be a genetic factor contributing to hypertension susceptibility in Filipinos." (PMID 37024851, 2023). "However, few studies have investigated the correlation between CYP2C19-rs3814637 and -rs11568732 polymorphisms and hypertension." (PMID 35814206, 2022). "Besides, some researchers have suggested a link between CYP2C19 polymorphisms and diseases, such as digestive tract cancer and essential hypertension." (PMID 25802476, 2015). "However, a study in Koreans found that CYP2C19*3 genetic variant reduced the risk of hypertension." (PMID 37024851, 2023). "In addition to the common polymorphisms (rs4244285, rs4986893) of CYP2C19 gene, other polymorphisms may also be associated with the susceptibility to hypertension." (PMID 37024851, 2023). "And the CYP2C19 IM genotypes (IM vs. EM: OR 1.523, 95% CI: 1.300-1.785, P < 0.001), PM genotypes (PM vs. EM: OR 2.127, 95% CI: 1.645–2.749, P < 0.001) may increase risk of hypertension." (PMID 37024851, 2023). "Additionally, studies have shown that the CYP2C19*3 defective allele may contribute to a reduced risk of developing essential hypertension." (PMID 35814206, 2022). "Univariate analysis identified age, hypertension, smoking, stent tortuosity, CYP2C19 poor metabolizer status and elevated TEG parameters (α-Angle and MA value) as significantly associated with ISR." (PMID 42037677, 2026). "Third, this study did not classify hypertensive patients and analyze the relationship between CYP2C19 gene polymorphisms and CAD risk in patients with different hypertension grades." (PMID 40715000, 2025). "The purpose of this study was to study the relationship between CYP2C19 genotypes and hypertension among Hakka population." (PMID 37024851, 2023). "And the CYP2C19 IM genotype (IM vs. EM: OR 1.514, 95% CI: 1.291–1.775, P < 0.001), PM genotype (PM vs. EM: OR 2.120, 95% CI: 1.638–2.743, P < 0.001), IM + PM genotypes (IM + PM vs. EM: OR 1.617, 95% CI: 1.390–1.882, P < 0.001) may increase risk of hypertension." (PMID 37024851, 2023). "And the CYP2C19 IM genotypes (IM vs. EM: OR 1.514, 95% CI: 1.291–1.774, P < 0.001), PM genotypes (PM vs. EM: OR 2.119, 95% CI: 1.637–2.743, P < 0.001), IM + PM genotypes (IM + PM vs. EM: OR 1.617, 95% CI: 1.390–1.881, P < 0.001) may increase risk of hypertension." (PMID 37024851, 2023). "The factors included age, BMI, smoking, alcohol intake, NSTEMI, hypertension, dyslipidemia, concomitant medication, CYP2C19*2 carriers, CYP2C19*17 carriers and metabolizer phenotype." (PMID 34384383, 2021). "The possibilities of hyperglycemia, hypercholesterolemia, hypertriglyceridemia, hypo-HDL-cholesterolemia, hyper-LDL-cholesterolemia and high blood pressure were not statistically associated with CYP2C19 genotypes." (PMID 38671468, 2024).
Hypertension (continued). "Therefore, future studies need to include larger sample size, include more parameters related to hypertension as much as possible, the classification of hypertension, and the analysis of full-length variation of CYP2C19 gene." (PMID 37024851, 2023). "Besides, intermittent PPI male users with age over 60 years old, hypertension, CKD and CYP2C19 IM type also suffered less risk of NACE compared with sustained PPI users." (PMID 33546595, 2021). "However, for a specific group of people with hypertension, there is currently no systematic conclusion regarding how the polymorphisms of the CYP2C19 gene increase the risk of CAD by influencing metabolic pathways, inflammatory responses, or vascular remodeling." (PMID 40715000, 2025). "We analyze risk factors include age, BMI (body mass index), smoking, alcohol intake, NSTEMI (non-ST-segment elevation myocardial infarction), hypertension, dyslipidemia, concomitant medication, CYP2C19*2 carriers, CYP2C19*17 carriers and metabolizer phenotype." (PMID 34384383, 2021). "However, age, BMI, smoking, alcohol intake, NSTEMI, hypertension, dyslipidemia, concomitant medication, CYP2C19*17 carriers, and metabolizer phenotype were no longer significantly associated with MACE." (PMID 34384383, 2021).
Cirrhosis (15 papers, 2015 to 2026). A chronic disorder of the liver in which liver tissue becomes scarred and is partially replaced by regenerative nodules and fibrotic tissue resulting in loss of liver function. "Despite these limitations, TDM-guided dosing (1 mg/L–5.5 mg/L) remains advised for high-risk subgroups (e.g., cirrhosis, CYP2C19 poor metabolizers) to mitigate hepatotoxicity risk documented in prospective studies." (PMID 40741951, 2025). "Among the five patients with confirmed liver disease, the presence of cirrhosis, cholangitis or liver abscess was associated with lower CYP2C19 activity compared to what’s expected based on genotype." (PMID 37361233, 2023). "Cirrhosis-induced physiological changes profoundly affect the pharmacokinetics of CYP2C19 and CYP3A4 substrate drugs, posing challenges to their clinical use." (PMID 41471097, 2025). "Background/Objectives: Cirrhosis significantly alters physiological function and drug metabolism, particularly for medications primarily metabolized by CYP2C19 and CYP3A4." (PMID 41471097, 2025). "Following validation of the developed PBPK model in healthy subjects, the model was applied to predict the pharmacokinetic profiles of CYP3A4 and CYP2C19 substrate drugs after intravenous or oral administration in 1000 virtual patients with cirrhosis." (PMID 41471097, 2025). "Cirrhosis patients have decreased levels of the enzyme CYP2C19, and these levels are adversely correlated with cirrhosis severity." (PMID 37967076, 2023). "CYP2C19*2/*2, the poor metabolizer, is related to the higher concentration, implying that CYP2C19 testing is still meaningful for precision medicine of Child–Pugh class C cirrhosis patients." (PMID 34572712, 2021). "Only CYP2C19 showed a very high reduction of 98%.The largest reduction was observed with most of the targets in thesevere grade of cirrhosis." (PMID 34428046, 2021). "CYP2C19*2/*2 contributed high concentrations, meaning that CYP2C19 testing for precision medicine of Child–Pugh class C cirrhosis patients." (PMID 34572712, 2021). "In a prospective study of 31 patients with hepatitis C virus (HCV)-positive chronic hepatitis or cirrhosis and 30 healthy volunteers, the interaction between chronic liver disease and the CYP2C19 genotype was assessed." (PMID 32906709, 2020). "It has been noted that levels of the enzyme CYP2C19 are reduced in patients with cirrhosis and, that levels inversely correlate with severity of cirrhosis." (PMID 27869108, 2016). "It has been found that levels of the enzyme CYP2C19 are reduced in patients with cirrhosis and that levels inversely correlate with severity of cirrhosis." (PMID 26501124, 2015). "One study demonstrated that CYP2C19, 2E1, 1A2 and 2D6 probe drugs concentrations were inversely correlated to the Child-Pugh score and another one demonstrated that phenacetin clearance decreased by 90% in patients with cirrhosis." (PMID 34867341, 2021). "Mavacamten, primarily metabolized by CYP2C19 and CYP3A4, poses challenges in patients with cirrhosis due to enzyme downregulation, which can significantly increase drug exposure." (PMID 41496082, 2026). "Compared with controls, the Km values of CYP1A2, CYP2A6, CYP2B6, CYP2C8, CYP2C19, CYP2E1, and CYP3A4/5 were higher in both in fibrosis and cirrhosis groups." (PMID 27203676, 2016). "Several previous studies reported that the activities of several CYPs, including CYP1A2, CYP2A6, CYP2D6, CYP2C19, CYP2E1, and CYP3A were decreased in cirrhosis patients relative to healthy subjects." (PMID 27203676, 2016). "Interestingly, drug-metabolizing enzymes were differentially sensitive towards liver diseases, as evidenced by drastically reduced CYP2C19 activity in patients with mild liver disease, whereas CYP2E1 activity only decreased in decompensated cirrhosis." (PMID 27754327, 2016).
Anxiety (13 papers, 2014 to 2025). Intense feelings of nervousness, tension, or panic often arise in response to interpersonal stresses. "For example, a long allele is associated with a better response to citalopram, paroxetine, fluoxetine, risperidone, and clozapine, while CYP2D6 and CYP2C19 variants are associated with antidepressant-induced symptoms, such as nightmares, anxiety, and panic attacks." (PMID 38002991, 2023). "CYP2C19-PM and UM showed a mild, non-significant improvement in anxiety symptoms." (PMID 33920985, 2021).
gastroesophageal reflux disease (13 papers, 2017 to 2025). A chronic disorder characterized by reflux of the gastric and/or duodenal contents into the distal esophagus. "Proton pump inhibitors (PPIs) are a mainstay treatment for gastroesophageal reflux disease (GERD) and are mainly metabolized by CYP2C19 in the liver." (PMID 30050742, 2018). "In accordance with unaltered CYP2C19 activity in patients with gastroesophageal reflux disease taking pantoprazole, weak inhibition by pantoprazole did not induce phenoconversion." (PMID 37361233, 2023). "Moreover, CYP2C19*17 was absent in all CYP2C:TG homozygotes, which is consistent with previous findings showing the lack of CYP2C19*17+TG diplotype in individuals with gastroesophageal reflux disease treated with omeprazole." (PMID 41599608, 2025). "Since PPIs are commonly used in the treatment of reflux esophagitis, gastroesophageal reflux disease (GERD), Zollinger–Ellison syndrome, non-ulcer dyspepsia, and NSAID-related damage, the healing process in the therapy of these diseases was predictably affected by CYP2C19 genotype." (PMID 33659048, 2021).
liver disease (11 papers, 2015 to 2024). "It is important to closely monitor dosing in adults, as the drug’s levels are unpredictable, owing to a variety of factors, including gender, age, liver disease, and potential genetic polymorphisms in CYP2C19." (PMID 35054368, 2022). "Liver disease and cancer are important causes of the PC of NMs to PMs for CYP2C19." (PMID 38668482, 2024). "CYP2C19 was the most sensitive to the presence of liver disease, as measured by the 80% decrease in mephenytoin metabolism in cirrhotic patients." (PMID 39062040, 2024). "A cocktail of four oral drugs, caffeine (CYP1A2), chlorzoxazone (CYP2E1), debrisoquin (CYP2D6), and mephenytoin (CYP2C19), were administered to 20 patients with different severity of liver disease and 20 health-matched controls." (PMID 39062040, 2024). "A scoring system tool that incorporates both CYP2C19 activity on a continuous scale, together with the inhibitory effect of DDIs and comorbidities (i.e., liver disease) will likely improve the pharmaco-genotype to phenotype translation." (PMID 37361233, 2023). "Activities of CYP2E1, CYP2D6, CYP1A2 and CYP2C19 were all found to decrease with increasing hepatic disease severity, their activities were differentially affected." (PMID 27754327, 2016). "In contrast, CYP1A2 activity was found to decrease linearly with decreasing liver functions and metabolism of mephenytoin by CYP2C19 was already severely impaired by 63% in patients with mild liver disease (Pugh score 5 or 6)." (PMID 27754327, 2016). "Moreover, of four P450 enzymes tested in patients with liver disease, metabolism by CYP2C19 was found to decrease at the earliest stage of disease." (PMID 26501124, 2015). "Also, the CYP2C19 genotype frequencies were not significantly different among patients with various underlying hepatic diseases." (PMID 29531644, 2018). "This study demonstrated that CYP1A2, CYP2C19, CYP2D6, and CYP2E1 enzyme activity was differentially affected by the presence of liver disease." (PMID 36901973, 2023). "The distribution of CYP2C19 genotype frequencies in Iranian healthy people and patients with various hepatic diseases was not significantly different." (PMID 29531644, 2018). "Consequently, these combined findings indicate that starting doses of CYP2D6, CYP2E1 and CYP3A4 substrates should be adjusted in patients with moderate or severe liver disease, whereas a dose reduction of CYP2C19 and CYP1A2 substrates should already be considered in milder forms of liver disease." (PMID 27754327, 2016). "PNPLA3 is an established genetic marker of progressive liver disease, but PNPLA3 mRNA expression did not correlate to CYP2C19 activity in this cohort (r = 0.07, p = 0.68)." (PMID 37361233, 2023).
Obesity (11 papers, 2017 to 2025). Accumulation of substantial excess body fat. "We showed that the CYP2C19 genotype might explain weight gain in citalopram patients, and it might become a projection tool for preventing weight gain and obesity, particularly in patients who are overweight." (PMID 35879764, 2022). "Further studies should utilize randomized controlled trials to study patients with DM/obesity and multiple MACE risk factors over a longer time period to provide a clearer perspective on the specific clinical utility of CYP2C19 genetic testing in comparison to standard treatment." (PMID 35647265, 2022). "However, the CYP2C19 metabolic enzyme activity decreased in patients with obesity, and the auto-inhibition of CYP2C19 may be limited (similar to PMs); therefore, a comparable exposure was observed after single or repeated doses." (PMID 36297422, 2022). "Our patient’s clopidogrel treatment failure may be due to a combination of impaired clopidogrel metabolism (due to presence of no-function CYP2C19 variant) and decreased inhibition of platelet reactivity (possibly by DM and obesity)." (PMID 35647265, 2022). "It should be noted that the CPIC guideline does not take into account DM/obesity when determining clinical utility of CYP2C19 genetic testing." (PMID 35647265, 2022). "The combined role of DM/obesity and no-function CYP2C19 genotype in clopidogrel treatment failure was also exhibited in a 2020 Egyptian randomized trial." (PMID 35647265, 2022). "Regardless, CYP2C19 genotype-guided treatment of ACS/PCI patients, with consideration of DM/obesity status, may provide effective individualized therapy compared to standard treatment." (PMID 35647265, 2022). "A recent research suggested that CYP2C19 activity is lower in patients with obesity versus nonobese controls and increased following RYGB-induced weight loss by measuring the plasma (3 h) 5-hydroxyomeprazole (5-OH-omeprazole)/omeprazole ratio." (PMID 36297422, 2022). "Thus, ACS patients with DM/obesity who have undergone PCI and are intermediate CYP2C19 metabolizers may yield better treatment outcomes if prescribed ticagrelor instead of clopidogrel." (PMID 35647265, 2022).